MPO (myeloperoxidase)
Diseases named in the same sentence as MPO in open-access papers (continued):
Sharing a sentence is not in itself a finding about the gene and the disease.
vasculitis (continued). "Species-dependency may be present in the development of PMA plus PTU-induced MPO-ANCA-associated vasculitis." (PMID 27375623, 2016). "The second is anti-neutrophil cytoplasmic antibody (ANCA)-associated vasculitis attributed to the levamisole component, myeloperoxidase (MPO) and proteinase 3 (PR3) positive, whose main manifestations are typical cutaneous findings, arthralgias, otolaryngologic involvement, and agranulocytosis." (PMID 27824551, 2016). "In addition, glomerular deposition of C3 in MASP‐2‐deficient mice with anti‐MPO vasculitis was similar to that in wild‐type mice." (PMID 27235854, 2016). "In addition, in the cases of atorvastatin or allopurinol, only MPO-ANCA-associated vasculitis has been reported previously." (PMID 25648906, 2015). "In these case series only one of the patients had MPO associated vasculitis." (PMID 25097791, 2014). "In an anti-MPO antibody-induced mouse vasculitis model, ANCAs are proven to be pathogenic." (PMID 25000985, 2014). "MPO-ANCA vasculitis caused by PTU is more common than that resulting from MMI." (PMID 24379039, 2013). "In addition, previous attempts to mirror the approach in murine anti-MPO vasculitis, whereby mice deficient in PR3 (and elastase) were used to raise antibodies to the target antigen, have been unsuccessful." (PMID 22247758, 2012). "Unclassifiable vasculitis with MPO-ANCA positivity and ILD may represent a novel variant of MPA." (PMID 24758294, 2014). "Hence, the MPs-associated MPO - hydrogen peroxide - chloride system may contribute to widespread endothelial cell damage in conditions of neutrophil activation as observed in vasculitis and sepsis." (PMID 24915973, 2014). "Hence, the microparticle-associated myeloperoxidase-hydrogen peroxide-chloride system may contribute to widespread endothelial cell damage in conditions of neutrophil activation as observed in vasculitis and sepsis." (PMID 24915973, 2014). "In addition, several pediatric cases with MPO-ANCA vasculitis caused by MMI have been reported." (PMID 24379039, 2013). "ANCA antibodies targeting neutrophil granule enzymes proteinase 3 (PR3) and myeloperoxidase (MPO) extend antibody-defined endophenotype concepts into vasculitis realms." (PMID 41562780, 2026). "Myeloperoxidase-antineutrophil cytoplasmic antibody (MPO-ANCA)-positive vasculitis frequently affects the kidney and the lung, with alveolar hemorrhage being fatal." (PMID 41629608, 2026). "Recently, based on a multicenter study by the European Vasculitis Study Group (EUVAS) in 2017, the diagnostic value of PR3- and MPO-ANCA immunoassays was found to be equal to or even exceed the diagnostic performance of IIF." (PMID 39658634, 2025). "Recent evidence links COVID-19 to the onset of autoimmune diseases, including anti-PR3 and anti-MPO vasculitis in pediatric cases." (PMID 41239211, 2025). "Similar to prior reports, PTU was confirmed as the culprit agent, with laboratory findings (positive p-ANCA and MPO positivity) mirroring established immunological patterns of drug-induced vasculitis." (PMID 41393668, 2025). "CRP and MPO-ANCA were selected as covariates based on previous reports indicating that they reflect disease activity in vasculitis and influence renal prognosis." (PMID 40136450, 2025). "Hydralazine-modified MPO was pathogenic, as demonstrated by splenocyte transfer in a mouse model of ANCA vasculitis." (PMID 40020049, 2025). "A total of 478 patients tested positive for MPO-ANCA, among whom 73 patients (15.2%) were identified with ANCA-associated vasculitis and underwent regular follow-up; 29 with MPA, 22 EGPA, and 22 GPA." (PMID 40959075, 2025). "Targeting proinflammatory extracellular DNA with DNase I to reduce inflammation and the deveopment of glomeruonephritis in MPO-ANCA Vasculitis." (PMID 40632882, 2025).
vasculitis (continued). "For example, research in AAV—an autoimmune disease characterised by autoantibodies against proteins on neutrophils and NETs—commonly uses an anti-myeloperoxidase IgG-induced vasculitis mouse model." (PMID 40429915, 2025). "Neutrophil percentage significantly predicted both elevated NLR (>3) and anti-MPO levels, reinforcing the core role of neutrophils in MPO-ANCA vasculitis." (PMID 41239211, 2025). "Several case reports have documented anti-MPO vasculitis with pulmonary and renal involvement in pediatric patients who tested positive for COVID-19." (PMID 41239211, 2025). "Consistent with other studies, all patients with hydralazine-associated ANCA vasculitis in this study were seropositive for MPO-ANCA and/or exhibited dual seropositivity for both MPO-ANCA and PR3-ANCA." (PMID 40020049, 2025). "The third one was a pediatric patient with a MPO-ANCA-vasculitis recurrence post-transplant who responded to eculizumab followed by ravulizumab and achieved remission." (PMID 40430184, 2025). "In this study, we focus exclusively on MPO-ANCA vasculitis, as this is the predominant type in Australia, which we can model in a well-established murine model of anti-MPO GN." (PMID 40632882, 2025). "It is one of the antineutrophil cytoplasmic antibody (ANCA)-associated vasculitis, characterized by pauci-immune necrotizing vasculitis and strong association with perinuclear ANCA (p-ANCA) targeting myeloperoxidase (MPO)." (PMID 39872577, 2024). "Herein, we demonstrate an increased prevalence and concentration of ANCA that are specific for LAMP-2 in children with PR3/MPO-ANCA-negative vasculitis affecting medium (MVV) and large (LVV) blood vessels." (PMID 38612581, 2024). "Our patient was initially diagnosed with MIS-C at the age of 12 years and presented with MPO-ANCA angiitis at the age of 14 years." (PMID 39280366, 2024). "Myeloperoxidase-antineutrophil cytoplasmic antibody (MPO-ANCA) vasculitis manifests as a neutrophilic inflammation impacting small vessels across multiple organs, notably the lungs, kidneys, and skin." (PMID 38357081, 2024). "The immunopathology of ANCA vasculitis is in part driven by autoantibodies to two known autoantigens, myeloperoxidase (MPO) and proteinase 3 (PR3)." (PMID 39015144, 2024). "Patient 1: A 73-year-old male, with known MPO-ANCA positive vasculitis under remission maintenance therapy with rituximab, presented with fatigue, dizziness, lower limb edema, gross hematuria and acute kidney injury to our nephrology clinic." (PMID 39300109, 2024). "The ratio of gut bacteria Bacteroidetes/Firmicutes is associated with worse outcomes in multiple autoimmune kidney diseases including lupus nephritis, MPO-ANCA vasculitis, and Goodpasture’s syndrome." (PMID 38732038, 2024). "Novel and less invasive alternative therapies aimed at reducing inflammation in AAV or prolonging the period of remission will be a more focused and strategic approach at targeting MPO-ANCA vasculitis." (PMID 38732038, 2024). "Patient 4: A 72-year-old female patient, with known MPO-ANCA positive vasculitis and remission maintenance therapy with rituximab, was sent to our nephrology ward with acute kidney injury and reduced general condition." (PMID 39300109, 2024). "A retrospective study conducted in North America, including 745 patients with IPF, demonstrated that 25–33% of patients who were initially diagnosed with IPF and MPO-ANCA positivity developed vasculitis symptoms within a median follow-up period of 18 months." (PMID 38791316, 2024). "We present a unique case of MPO-ANCA vasculitis in a 77-year-old female characterized by glomerulosclerosis, rapidly progressive renal failure necessitating hemodialysis (HD), bullous skin lesions, and hypoxic respiratory failure." (PMID 38357081, 2024). "This was consistent with the findings from our study, which reported that 77 of 101 patients with positive anti-MPO antibodies had vasculitis as their primary diagnosis." (PMID 37676628, 2024).
vasculitis (continued). "In a 23-year-long, large-scale study involving patients with either MPO- or PR3-ANCA vasculitis, kidney, lung, and gastrointestinal involvement were reported in only 114, 72, and 5 patients, respectively, thus highlighting the rarity of these complications." (PMID 39280366, 2024). "Overall disease activity at diagnosis was higher in PR3-ANCA and MPO-ANCA-seropositive individuals compared with ANCA-negative vasculitis." (PMID 38886004, 2024). "Early recognition and timely treatment are pivotal in mitigating the dire consequences of this condition, emphasizing the importance of considering MPO vasculitis in patients with rapidly deteriorating renal function." (PMID 38357081, 2024). "We also found renal involvement (hematuria and proteinuria), a history of asthma, and positivity for antineutrophil cytoplasmic antibodies (p-ANCA) to MPO, raising a suspicion of ANCA-associated vasculitis." (PMID 39090138, 2024). "Only recently, more than 40 years after their presence in vasculitis was discovered, a role for ANCA specificity towards PR3 and MPO in predicting disease outcomes in ANCA-associated SVV is being recognized." (PMID 38612581, 2024). "Detailed humoral and cellular immunity tests, including angiitis-specific antibodies, showed MPO-ANCA seropositivity, and anti-GBM seronegativity, with normal peripheral blood smear immunophenotype." (PMID 39280366, 2024). "Anti-myeloperoxidase and anti-histone antibodies were ordered to further confirm and classify the vasculitis as drug induced." (PMID 38512508, 2024). "A big step forward is distinguishing new AAV phenotypes based on the ANCA specificity and significant advances in identifying the nuances between PR3-ANCA and MPO-ANCA vasculitis." (PMID 39257888, 2024). "We also identified a few anti-kinesin autoantibodies specifically associated with anti-MPO-ANCA positivity and with vasculitis activity." (PMID 37895021, 2023). "There was no increase in circulating MPO levels in diseased mice compared with baseline, which is in keeping with findings in patients with MPO vasculitis." (PMID 36154801, 2023). "Whatever the reasons for the differing results in the nephrotoxic nephritis model, the murine anti-MPO model of vasculitis more closely resembles ANCA vasculitis, both histologically and in terms of the disease-inducing mechanism." (PMID 36154801, 2023). "The aim of the current study was first to assess if myeloid-specific Mcl1 was required in murine anti-MPO vasculitis." (PMID 36154801, 2023). "Crescentic glomerulonephritis characterizes both autologous nephrotoxic nephritis and anti-MPO vasculitis." (PMID 36154801, 2023). "An additional prospective cohort study comparing 31 patients with cocaine/levamisole-induced vasculitis and 45 patients with idiopathic vasculitis found that the cohort using cocaine were more likely to be MPO positive (100% vs 67%)." (PMID 37026037, 2023). "According to current studies, it has been suggested that intravenous immunoglobulin (IVIG) therapy has a positive effect in patients with MPO-ANCA vasculitis." (PMID 38139045, 2023). "All anti-EPX/anti-MPO double-positive AEOSA+/ANCA+ sera (5/5) were found in patients with a history of thyroid disease or vasculitis." (PMID 37153639, 2023). "This link was stronger for anti-MPO/anti-EPX double-positive patients as all such patients had a history of thyroid disease or vasculitis." (PMID 37153639, 2023). "We have demonstrated that mice with an inactive p110δ are protected from vasculitis induced by passive transfer of anti‐MPO antibody." (PMID 35818684, 2023). "In summary, protection from disease in Mcl1ΔMyelo mice is likely to be due to effects on both neutrophils and monocytes in the anti-MPO vasculitis model." (PMID 36154801, 2023). "The majority of renal presentations are consistent with a diagnosis of MPA(typically an MPO-ANCA vasculitis), or renal-limited vasculitis, with onlyone case of GPA in a patient with SSc." (PMID 36743820, 2023).
vasculitis (continued). "A study performed by the EUVAS (European Vasculitis Study Group) in 2016 compared IIF-ANCA techniques performed at two sites to eight solid-phase immunoassays for MPO- and PR3-ANCA." (PMID 37493768, 2023). "ANCA(−) vasculitis also shows a higher percentage of sclerotic lesions and interstitial fibrosis, similar to the damages found in MPO-ANCA vasculitis." (PMID 36294902, 2022). "Conversely, the 2020 international consensus on ANCA testing in EGPA suggested that the MPO-ANCA is neither sensitive nor specific enough to identify “vasculitic” or “eosinophilic” EGPA, although patients with MPO-ANCA have more features of vasculitis." (PMID 35833130, 2022). "Contrastingly, myeloperoxidase (MPO) and proteinase 3 (PR3) antibodies are features of ANCA-associated vasculitis (granulomatosis with polyangiitis, microscopic polyangiitis, and eosinophilic granulomatosis with polyangiitis)." (PMID 36419545, 2022). "Its antagonist prevents glomerulonephritis in a model of anti-MPO-induced rat, and the presence is important in the pathogenesis of vasculitis." (PMID 36034958, 2022). "In the current study, we tried to investigate the role of S100A8/A9 and S100A12 in MPO-ANCA-positive vasculitis." (PMID 36088289, 2022). "In conclusion, the serum and urine levels of S100A8/A9 and S100A12 in patients with active MPO-ANCA-positive vasculitis were elevated and correlated with the severity of the disease." (PMID 36088289, 2022). "There was also a reported case of myeloperoxidase-vasculitis and rhabdomyolysis after Pfizer-BioNTech COVID-19 mRNA vaccination, whose biopsy demonstrated PICGN in addition to a severe acute tubular lesion with myoglobin cast and interstitial inflammation." (PMID 36544502, 2022). "ANCAs directed against proteinase 3 (PR3) or myeloperoxidase (MPO) bind their cell surface-presented antigen, activate neutrophils, and cause vasculitis." (PMID 36125911, 2022). "The two main ANCA auto-antigens involved in the pathogenesis of vasculitis are myeloperoxidase (MPO-ANCA) and proteinase 3 (PR3-ANCA)." (PMID 34943555, 2021). "We have recently shown that Tregs induced by MPO-presenting tolerogenic DCs can be used to inhibit established anti-MPO immunity and vasculitis in a pre-clinical model of MPO-AAV." (PMID 34394071, 2021). "For instance, the upper respiratory system is more frequently affected in PR3-ANCA(+) and kidneys predominated in MPO-ANCA(+) vasculitis." (PMID 35127750, 2021). "The prevalence rate of AS was significantly higher in MPO-AAV patients with renal involvement at more than 1 year after the onset of vasculitis than in control CKD patients." (PMID 33481903, 2021). "Our model has some differences to other published models of anti-MPO vasculitis, including the use of LPS and GCSF and these are possible factors." (PMID 36751530, 2021). "The so-called myeloperoxidase-antineutrophil cytoplasmic antibodies play a role in the pathogenesis of different forms of vasculitis such as glomerulonephritis and vasculitis of the upper and lower respiratory tract." (PMID 34829676, 2021). "This study aimed to examine the development of AS in patients with myeloperoxidase-AAV (MPO-AAV) with renal involvement at more than 1 year after the onset of vasculitis." (PMID 33481903, 2021). "Anti-myeloperoxidase vasculitis (MPO-AAV) is a life-threatening autoimmune disease which causes severe inflammation of small blood vessels, mainly in the kidney." (PMID 34394071, 2021). "Previous work in murine anti-myeloperoxidase vasculitis has shown a role for the alternative pathway complement component factor B and the anaphylatoxin C5a." (PMID 36751530, 2021). "The first evidence of the pathogenic role of complement activation in AAV was provided by the mouse model of anti-myeloperoxidase (MPO) antibodies-induced vasculitis." (PMID 33451011, 2021). "First, we attempted to reproduce previous findings on the role of factor B in anti-myeloperoxidase vasculitis." (PMID 36751530, 2021).
vasculitis (continued). "In ANCA vasculitis, anti-MPO antibodies cross-reactive to moesin in glomerular endothelial cells lead to endothelial cell activation and increased glomerular moesin expression." (PMID 33669337, 2021). "The DCs significantly decreased vasculitis and MPO-specific immunity, including effector CD4 T cell activation, proliferation, survival and pro-inflammatory cytokine production, as well as CD8 T cell and B cell responses." (PMID 34394071, 2021). "First, we have failed to reproduce previous research showing an essential role for factor B in the anti-myeloperoxidase vasculitis model." (PMID 36751530, 2021). "Recently, we demonstrated that administration of ex vivo-generated antigen-presenting tolerogenic DCs can induce selective, MPO-specific immunosuppression and attenuate vasculitis in mice." (PMID 34394071, 2021). "MPO-AAV predominates in southern Europe and Asia-Pacific, is genetically weakly associated with HLA-DQ, mainly occurs as a single event, and vasculitis is mostly limited to the kidney." (PMID 34394071, 2021). "It is not clear why our data differ so significantly from a previous report showing a requirement for factor B in the development of anti-MPO vasculitis." (PMID 36751530, 2021). "The critical importance of endogenous Tregs as negative regulators of anti-MPO autoimmunity and vasculitis has been confirmed in experimental MPO-AAV." (PMID 34394071, 2021). "For example, immunization with a TLR9 ligand enhanced MPO-ANCA-induced vasculitis and increased immune response and organ damage in a mouse model." (PMID 33420306, 2021). "Second, we examined the role of VISTA in this model, in order to see if the protection in the nephrotoxic nephritis model extended to anti-myeloperoxidase vasculitis." (PMID 36751530, 2021). "An intriguing finding has been made with regard to MPO-ANCA vasculitis by demonstrating that CD4+ T cells as well as B cells derived from patients with MPO-AAV recognize linear epitopes in a restricted region of human MPO (MPO447–461)." (PMID 34204207, 2021). "Studies have shown that PR3-ANCAs or MPO-ANCAs are found in most patients with vasculitis, and these forms of ANCAs are the primary determinants of AAV pathogenesis." (PMID 33746569, 2021). "This study aimed to examine the development of AS (atherosclerotic lesion) in MPO-AAV patients with renal involvement at more than 1 year after the onset of vasculitis and assess the effect of AS on long-term prognosis." (PMID 33481903, 2021). "The co-existing autoimmune conditions were Sjogren’s syndrome (n=1), Myeloperoxidase (MPO) positive vasculitis (n=1) and myasthenia gravis (n=1)." (PMID 34858387, 2021). "The AS prevalence rate was significantly higher in MPO-AAV patients at more than 1 year after the onset of vasculitis than in control CKD patients." (PMID 33481903, 2021). "Anti-MPO-ILD patients are at risk of progression in a definite rheumatic disease, mainly ANCA-associated vasculitis, in a variable range of time." (PMID 34207641, 2021). "On the basis of these findings, an involvement of MPO is discussed in the pathogenesis of numerous disease scenarios including atherosclerosis, vasculitis, rheumatoid arthritis, neurodegenerative diseases, etc.." (PMID 34829676, 2021). "PR3-ANCA vasculitis is characterized by a predominant involvement of the upper respiratory tract, and in comparison to MPO-ANCA vasculitis less frequently affects the lower respiratory tract and the kidneys." (PMID 33023023, 2020). "We present a case of PTU-induced anti-MPO and PR3 positive ANCA vasculitis with associated anti-GBM antibodies, IgA nephropathy and an IgG4 interstitial infiltrate." (PMID 32703233, 2020). "There are some other molecules like IL-10, which have a distinct expression level between PR3-ANCA and MPO-ANCA vasculitis." (PMID 33023023, 2020).